PTCSC3 (papillary thyroid carcinoma susceptibility candidate 3)
Diseases named in the same sentence as PTCSC3 in open-access papers (continued):
Sharing a sentence is not in itself a finding about the gene and the disease.
tumor (continued). "ENSG00000259104.2 (PTCSC3), which is downregulated in the tumor samples (log2 fold change −1.40; adj." (PMID 28490781, 2017). "Re-expression of PTCSC3 in TC cells represses tumor growth and influences the transcription of some genes associated with DNA replication, recombination, repair, cellular movement, tumor morphology, and cell death." (PMID 27802187, 2017). "The risk allele (T) of rs944289 is strongly related to the down-regulation of PTCSC3 in TC tumor tissues." (PMID 27802187, 2017). "In the present study, PTCSC3 as a tumor suppressor was investigated as a competing endogenous RNA for miR-574-5p." (PMID 23599737, 2013). "Thus, it can be stipulated that the oppressive effect of PTCSC3 on tumor progression can be connected to lncRNA HOTAIR." (PMID 36359888, 2022). "Interestingly, the tumor suppressor PTCSC3 was studied along with LINC-PINT in gastric cancer tissues, inhibiting tumor growth and stemness when both were over-expressed." (PMID 35978835, 2022). "By contrast, as a tumor-suppressing lncRNA, PTCSC3 down-regulated STAT3 expression." (PMID 35372012, 2022). "To further investigate whether PTCSC3 performs an anti‐tumour function via PGK1, we overexpressed PGK1 in PTCSC3‐overexpressing TPC‐1 and BCPAP cells, and their protein expression was confirmed by Western blot." (PMID 34337858, 2021). "Consistently, PTCSC3 overexpression suppressed tumour progress in vivo." (PMID 34337858, 2021). "PGK1 overexpression impaired the inhibitory effect of PTCSC3 in tumour progression." (PMID 34337858, 2021). "The experimental data in our study proved that PTCSC3 functions as a tumour suppressor, overexpression of PTCSC3 could inhibit PTC cell proliferation and development in vitro and in vivo." (PMID 34337858, 2021). "LncRNA PTCSC3 is a known tumor suppressor, while its roles in other human diseases are unclear." (PMID 31196168, 2019). "The expression levels of PTCSC2 and PTCSC3 are strictly thyroid-specific, and they may serve as promising tumor suppressors." (PMID 29416703, 2018). "However, the expression level of LINC02555 and PTCSC3 were higher in normal lung tissues, reflecting they may serve as repressive roles in tumor growth or progression." (PMID 35372012, 2022). "The overexpression of lncRNA PTCSC3 could inhibit PTC cell growth and affected the expression of genes involved in DNA replication, recombination and repair, cellular movement, tumor morphology, and cell death, implying that lncRNA PTCSC3 has the characteristics of a tumor suppressor." (PMID 23725405, 2013). "Nevertheless, the tumor suppression mechanism of PTCSC3 is currently unknown." (PMID 24144365, 2013). "PTCSC3 restoration negatively regulates the expression of the EF-hand calcium-binding protein S100A4, thereby limiting tumor invasiveness and reducing angiogenesis and extracellular matrix remodeling." (PMID 41489907, 2026). "Correlation analysis in the TCGA-KIRC dataset revealed that RP11-528A4.2 was negatively correlated with patient age, LINC00645 was negatively correlated with tumor stage, PTCSC3 was positively correlated with gender, and AP000696.2 was positively correlated with tumor stage, T stage, and M stage." (PMID 37968670, 2023). "It is therefore possible to hypothesize that PTCSC3 through inducing LINC-PINT, inhibits the expression of miR-21, HIF-1, and ATG5, and thereby exerts anti-tumor functions in GC cells." (PMID 37644548, 2023). "Interestingly, PTCSC3 is located 3.2 kb downstream of rs944289 at 14q.13.3 and has lower expression in PTC thyroid tumours, suggesting a tumour-suppressor role." (PMID 35255942, 2022). "Expectedly, PTCSC3 led to a markedly decrease in glucose uptake, lactate production and ATP level in both TPC‐1 and BCPAP cell lines, and the lactate levels in tumour tissues from control mice were substantially higher than those in PTCSC3 overexpression group." (PMID 34337858, 2021).
tumor (continued). "PTCSC3 level was found to be significantly lower in PTC than in normal thyroid tissue, which corresponds well with its tumor suppressor function." (PMID 33551988, 2020).
cancer (14 papers, 2013 to 2025). A tumor composed of atypical neoplastic, often pleomorphic cells that invade other tissues. "In effect, PTCSC3 should also interact with multiple factors to regulate LSCC cell proliferation because HOTAIR overexpression only partially rescued the inhibitory effect of PTCSC3 overexpression on cancer cell proliferation." (PMID 31171714, 2019). "The expression level of PTCSC3 in glioma cancer, like in other cancers, shows a decreasing pattern." (PMID 37644548, 2023). "Our date enriched our understanding on the functionality of HOTAIR in cancer biology and suggested that overexpression of PTCSC3 may serve as a therapeutic target for LSCC." (PMID 31171714, 2019). "In addition, HOTAIR overexpression attenuated the inhibitory effects of PTCSC3 overexpression on cancer cell proliferation (P<0.05)." (PMID 31171714, 2019). "In addition, HOTAIR overexpression reduced the inhibitory effects of PTCSC3 overexpression on cancer cell proliferation." (PMID 31171714, 2019). "Therefore, PTCSC3 as the upstream inhibitor of HOTAIR should also interact with other factors to inhibit the inhibitor effects of HOTAIR down-regulation (as a result of PTCSC3 overexpression) on cancer cell migration and invasion." (PMID 31171714, 2019). "An increasing number of studies has demonstrated that miR-574-5p can be sponged by lncRNA, like lncRNA PTCSC3 and lncRNA MFI2-AS1, to modulate growth and metastasis of cancer cells." (PMID 32614631, 2020). "Despite many reports on PTCSC3’s role in the pathogenesis of both cancers and non-cancerous diseases, there is currently no comprehensive and detailed overview of PTCSC3." (PMID 37644548, 2023). "Thus, the lncRNA PTCSC3 regulates the pathogenesis of ATC by modulating STAT3 signalling and CSCs phenotype of cancer cells." (PMID 33126409, 2020). "In addition, PTCSC3 inhibits stem cell properties of ATC (8050C) cells, as the expression rate of CD133 and MDR-1 (cancer stem cell markers) was decreased." (PMID 33126409, 2020). "However, another study showed that the comparison of PTCSC3 expression in different stages of cancer do not show any significance in BC." (PMID 37644548, 2023). "However, cancer cell invasion and migration were not significantly affected by PTCSC3 overexpression (data not shown)." (PMID 31171714, 2019). "We performed preliminary analysis (deep sequencing-based transcriptome analysis) and found that PTCSC3 was down-regulated in LSCC and negatively correlated with HOTAIR (data not shown), which is an oncogenic lncRNA in cancer." (PMID 31171714, 2019).
PTCSC3 also shares sentences with these, for which no sentence is quoted: hepatocellular carcinoma (3 papers); anaplastic thyroid cancer (1); autoimmune disease (1); basal cell carcinoma (1); Colon Cancer (1); colorectal cancer (1); digestive system cancer (1); esophageal squamous cell carcinoma (1); liver cancer (1); lung carcinoma (1); non-small cell lung carcinoma (1); oral cavity cancer (1); pancreatic cancer (1); papillary carcinoma (1); rectal tumors (1); triple-negative breast carcinoma (1).